IL33 (interleukin 33)
Diseases named in the same sentence as IL33 in open-access papers (continued):
Sharing a sentence is not in itself a finding about the gene and the disease.
proliferative retinopathies (4 papers, 2022 to 2024). "Loss of IL-33 in a murine model of retinopathy reduces pathological retinal neovascularization, which can be specified to the role of IL-33 in endothelial cells." (PMID 35589941, 2022). "Because the biological activity of these mature IL-33 variants is 30- to 60-fold greater than that of full-length IL-33, we used human microvascular endothelial cells (HRMVECs) and mouse oxygen-induced retinopathy models to investigate the influence of each of these IL-33 variants on angiogenesis." (PMID 39085349, 2024). "The research concludes that IL-33, especially its enzyme-processed forms, plays a key role in the development of proliferative retinopathies by promoting abnormal blood vessel growth in the eye." (PMID 39085349, 2024). "The IL-33-NF-κB-VCAM-1-JunB-IL-8/CXCL1 signaling unravels the advanced strategies in the amelioration of proliferative retinopathies." (PMID 37179352, 2023). "Thus, our results demonstrate that proteolytic processing by inflammatory proteases induces IL-33 activity in proliferative retinopathies." (PMID 39085349, 2024). "This new understanding of IL-33’s function could lead to new treatments for proliferative retinopathies." (PMID 39085349, 2024). "Therefore, we investigated the involvement of PKCμ-p38 MAPK-α-catenin signaling in OIR-induced proliferative retinopathy and the effect of IL-33 deletion on this signaling." (PMID 36899839, 2023). "Thus, our study results suggest that blockade or inhibition of IL-33 cleavage by neutrophil proteases could help mitigate pathological angiogenesis in proliferative retinopathies." (PMID 39085349, 2024). "As we observed an induced expression of IL-8 by IL-33 in HRMVECs, we looked for the expression of various CXCL proteins in the murine model of oxygen-induced retinopathy using RNA sequencing." (PMID 37179352, 2023).
psychiatric disorder (4 papers, 2021 to 2024). A disorder characterized by behavioral and/or psychological abnormalities, often accompanied by physical symptoms. "According to several studies, the serum IL-33 levels in depressive and other psychiatric disorder patients were higher when compared to healthy controls (HCs)." (PMID 38216957, 2024). "Similarly, the interleukin-1 family cytokine interleukin-33 (IL-33), produced by developing astrocytes and necessary for normal synapse numbers and neural circuit development, has been implicated in various neurodevelopmental and psychiatric disorders, including ASD and SZ." (PMID 38132147, 2023). "A recent theory highlights the role of the IL-33/IL-31 axis in different autoimmune disorders; immune system impairment as a comorbidity in psychiatric disorders was reported by several authors." (PMID 33810498, 2021).
brain diseases (3 papers, 2018 to 2024). "In brain diseases, the ST2 receptor is activated by the consequent production of IL-33, promoting the secretion of IL-13, which is associated with type 2 inflammation and is an ideal target for inhibiting the inflammatory response." (PMID 38542222, 2024). "IL-33 is a potent inducer for the Th2 immune response which includes defence mechanism in brain diseases." (PMID 29507527, 2018). "Therefore, MCs and microglia in the CNS are a source of pro-inflammatory cytokines, including TNF and IL-33, that mediate many brain diseases." (PMID 38542222, 2024). "In the CNS, IL-33 is highly expressed by glial cells, activates ILC2, and plays an important role in brain diseases." (PMID 38542222, 2024). "There are several insights that point out the potential of IL-33/ST2 pathway for novel biomarker discovery and therapeutic target in diverse brain diseases." (PMID 29507527, 2018).
vasculopathy (3 papers, 2020 to 2024). "For example, we identified a subnetwork involving endothelial IL33 ↔ macrophage CXCL13 ↔ fibroblast CDKN1A; each component within this subnetwork is associated with vasculopathy, and here we suggest that they interact during metabolic pathology in the aorta." (PMID 34692110, 2020). "Disrupting IL-33 signaling or targeting IL-33+ fibroblasts in perivascular niches may prevent allograft fibrosis and vasculopathy." (PMID 39621314, 2024).
peripheral neuropathy (2 papers, 2016 to 2022). A disorder affecting the peripheral nervous system. "Oligodendrocytes can modulate pain through interleukin-33 (IL-33) expression, under peripheral neuropathy." (PMID 35308613, 2022).
head and neck tumors (1 paper, 2024). "In this study, it was found that IL-1α, IL-1β, IL1R1, IL1RL1, IL1F10, IL33, CASP1, and AIM2 were highly expressed in head and neck tumors, while IL1RN, IL1RAPL1, IL1RAPL2, IL18BP, IL18R1, and IL18RAP were low in expressed, which is consistent with previous literature." (PMID 39461030, 2024).
neurodevelopmental disorder (1 paper, 2022). A behavioral and cognitive disorder with onset during the developmental period that involves impaired or aberrant development of intellectual, motor, or social functions. "More convincing evidence, such as perturbations of IL-33 at different time points or complete gene knockout, is needed to support this possibility; IL-33’s critical role in microglial phagocytosis makes it a promising target for neurodevelopmental disorders." (PMID 36439205, 2022).
IL33 also shares sentences with these, for which no sentence is quoted: Allergy (115 papers); chronic rhinosinusitis (17); idiopathic pulmonary fibrosis (16); acute myocardial infarction (12); chronic periodontitis (6); hypertrophy (6); cardiomyopathy (4); chronic rhinosinusitis with nasal polyps (4); cognitive disorder (4); hepatitis C (4); nonalcoholic steatohepatitis (4); obstructive sleep apnea (4); Parkinson disease (4); primary immunodeficiency (4); atrial fibrillation (3); gestational diabetes (3); glaucoma (3); glomerulonephritis (3); hemorrhage (3); hypersensitivity pneumonitis (3); kidney injury (3); multiple myeloma (3); musculoskeletal diseases (3); necrotizing enterocolitis (3); synovitis (3); Ventricular hypertrophy (3); acute bronchiolitis (2); acute liver failure (2); acute respiratory failure (2); alcohol abuse (2).
A further 159 diseases each share a sentence with IL33 in 2 papers or fewer.